SLC4A3 (solute carrier family 4 member 3)
Description:
Sodium-independent anion exchanger which mediates the electroneutral exchange of chloride for bicarbonate ions across the cell membrane. May be involved in the regulation of intracellular pH, and the modulation of cardiac action potential.
Synonyms: AE3; SLC2C; CAE3/BAE3; SQT7
Tractability: Small molecule: a structure with a bound ligand is known. Antibody: UniProt places it where antibodies can reach, with high confidence; its Gene Ontology location is reachable by antibodies, with high confidence; UniProt predicts a signal peptide or a membrane-spanning region. PROTAC: ubiquitination databases record sites on it; its protein half-life has been measured.
Gene: Protein-coding gene on chromosome 2 (219,627,011 to 219,641,980, forward strand). Ensembl gene ENSG00000114923.
Subcellular location: Cell membrane; Cell membrane (Isoform CAE3)
Subcellular location (Human Protein Atlas): Nucleoplasm
Pathways (Reactome):
Transport of small molecules: Bicarbonate transporters
Gene Ontology:
Molecular function: bicarbonate transmembrane transporter activity; protein binding; solute:inorganic anion antiporter activity; chloride:bicarbonate antiporter activity; monoatomic anion transmembrane transporter activity
Biological process: bicarbonate transport; cardiac conduction; pH reduction; regulation of cardiac muscle cell action potential; cardiac muscle cell action potential; regulation of intracellular pH; transport across blood-brain barrier; chloride transmembrane transport; monoatomic anion transmembrane transport; monoatomic anion transport; transmembrane transport
Cellular component: external side of plasma membrane; plasma membrane; membrane
Genetic constraint (gnomAD): Loss-of-function variants: 47 observed, 107.39 expected, observed/expected ratio (o/e) 0.44, 90% interval 0.34 to 0.56. The upper end of that interval is the gene's LOEUF score, 0.56, which puts it in group 2 of 6, group 1 being the genes least tolerant of losing a copy. Missense variants: 1,282 observed, 1,634.8 expected, observed/expected ratio (o/e) 0.78, 90% interval 0.75 to 0.82. Synonymous variants: 683 observed, 692.44 expected, observed/expected ratio (o/e) 0.99, 90% interval 0.93 to 1.05.
Gene-disease validity (ClinGen):
ClinGen rates the evidence that SLC4A3 causes each of these diseases.
short QT syndrome (autosomal dominant): Moderate.
Homologues: Orthologues: chimpanzee SLC4A3 (99% identical), guinea pig SLC4A3 (96% identical), mouse Slc4a3 (96% identical), rat Slc4a3 (95% identical), dog SLC4A3 (95% identical), pig SLC4A3 (94% identical), rabbit SLC4A3 (91% identical), tropical clawed frog slc4a3 (52% identical), zebrafish slc4a3 (47% identical), Drosophila melanogaster Ae2 (38% identical), Drosophila melanogaster Ndae1 (30% identical), Caenorhabditis elegans abts-1 (28% identical), and 1 more. Paralogues in human: SLC4A2 (59% identical), SLC4A1 (42% identical), SLC4A7 (33% identical), SLC4A10 (32% identical), SLC4A4 (32% identical), SLC4A8 (31% identical), SLC4A5 (30% identical), SLC4A9 (27% identical), SLC4A11 (17% identical).
Diseases named in the same sentence as SLC4A3 in open-access papers:
SLC4A3 is named in the same sentence as 47 diseases in open-access papers, as found by Europe PMC text mining. Sharing a sentence is not in itself a finding about the gene and the disease. The quoted sentences say what the papers report.
heart failure (5 papers, 2013 to 2017). Inability of the heart to pump blood at an adequate rate to meet tissue metabolic requirements. "Loss of the AE3 Cl−/HCO3− exchanger (Slc4a3) in mice causes an impaired cardiac force-frequency response and heart failure under some conditions but the mechanisms are not known." (PMID 28779178, 2017).
short QT syndrome (5 papers, 2022 to 2025). A genetic disease of the electrical system of the heart that consists of a constellation of signs and symptoms, consisting of a short QT interval on an EKG (< 300 ms) that does not significantly change with heart rate, tall and peaked T waves, and a structurally normal heart. "Although variants in SLC4A3 have been implicated in short QT syndrome and other cardiac arrhythmias, the clinical relevance of such variants in pediatric populations remains poorly defined." (PMID 41328150, 2025). "The SLC4A3 protein is a plasma membrane anion exchange protein with mutations responsible for short QT syndrome and elevated risk of ventricular fibrillation and sudden cardiac death." (PMID 39774334, 2025). "This sequence is present in a transmembrane helix of all three described isoforms of the cardiac protein SLC4A3 (UniProtKB: P48751), an anion exchange protein that is associated with short QT syndrome." (PMID 35314694, 2022). "In one of these loci where SigNet and PoPS differ, both selected genes may be causal: at the locus where SigNet selects SLC4A3, responsible for a Mendelian form of short QT syndrome, PoPS selects DES (desmin), responsible for a Mendelian form of cardiomyopathy." (PMID 39774334, 2025).
epilepsy (3 papers, 2013 to 2024). A brain disorder characterized by episodes of abnormally increased neuronal discharge resulting in transient episodes of sensory or motor neurological dysfunction, or psychic dysfunction. "Other NOVA-NMD related targets in which gene mutations have been implicated in human epilepsy include the anion transporters SLC4a10 and SLC4a3." (PMID 23359859, 2013).
retinal degeneration (3 papers, 2011 to 2024). Degeneration of the retina. "Despite the association of aberrant SLC4A3 with retinal degeneration in two model species, mouse and dog, similar studies investigating possible involvement of the gene in human retinal degeneration have not been reported to date." (PMID 27211793, 2016). "This study was undertaken to investigate if SLC4A3 coding variants were implicated in human retinal degeneration." (PMID 27211793, 2016). "SLC4A3 has been shown to cause retinal degeneration in a genetically engineered knockout mouse, and in a naturally occurring form of canine progressive retinal atrophy considered to be the equivalent of retinitis pigmentosa in humans (RP)." (PMID 27211793, 2016). "Screening of the exons of SLC4A3 in DNA samples from 200 patients with retinal degeneration resulted in the identification of three rare variants that are predicted (by in silico methods) to be potentially deleterious." (PMID 27211793, 2016). "The SLC4A3 gene remains an excellent candidate gene for human retinal degeneration and the variants identified will help to build a picture of its potential contribution." (PMID 27211793, 2016). "Furthermore, animal models demonstrate that knockout or mutations of Slc4a3 can induce retinal degeneration, progressing to retinitis pigmentosa, thereby positioning SLC4A3 as a potential candidate gene for human retinal diseases." (PMID 39033175, 2024). "SLC4A3 remains an excellent candidate gene for human retinal degeneration, and with the advent of whole exome and whole genome sequencing of cohorts of molecularly unsolved patients with syndromic and non-syndromic forms of retinal degeneration, SLC4A3 may yet be implicated in human disease." (PMID 27211793, 2016). "Interestingly, the effect of SLC4A3-deficiency has been described in a knockout mouse model showing that a selective inner retina defect is followed by photoreceptor degeneration, similar to the retinal degeneration seen in many forms of PRA and RP." (PMID 21738669, 2011). "A knockout mouse model for Slc4a3 identified SLC4A3 as a candidate gene for human vitreoretinal degenerations based on their findings of blindness and retinal degeneration in knockout mice." (PMID 27211793, 2016). "We therefore screened SLC4A3 in a cohort of human patients with predominantly recessive retinal degeneration currently lacking a molecular diagnosis in order to determine whether mutations in this gene cause a significant proportion of retinal degeneration in humans." (PMID 27211793, 2016). "Evidence from the mouse and canine disease models suggest the SLC4A3 gene is an excellent candidate for human retinal degeneration." (PMID 27211793, 2016). "The identification of a frameshift insertion in SLC4A3 in GR dogs with PRA, that is likely to be a major susceptibility locus for PRA in this breed, endorses the status of this gene as a candidate for human retinal degenerations." (PMID 21738669, 2011). "SLC4A3 is important for retinal function and has not previously been associated with spontaneously occurring retinal degenerations in any other species, including humans." (PMID 21738669, 2011). "While it appears that the variants in SLC4A3 identified in this study are unlikely to cause AR RP in the cohort screened in isolation, we cannot fully exclude these variants or the gene as a candidate for retinal degeneration." (PMID 27211793, 2016). "Finally, it is also possible that mutant SLC4A3 actually causes a syndromic or non-syndromic form of retinal degeneration in humans that would not be clinically classified as RP." (PMID 27211793, 2016).
Blindness (2 papers, 2007 to 2016). Blindness is the condition of lacking visual perception defined as a profound reduction in visual perception. "Identification of Slc4a3 as underlying a previously unrecognized cause of blindness suggests this gene as a new candidate for a subset of hereditary vitreoretinal retinal degeneration." (PMID 17786210, 2007).
cardiomyopathy (2 papers, 2013 to 2025). A disease of the heart muscle or myocardium proper. "For example, the presence of congenital heart disease could possibly be ascribed to the deregulation of the DES, LDB3, POPDC2 and SLC4A3 genes, all of which have previously been associated with cardiac function and pathology, such as cardiomyopathy." (PMID 23816241, 2013).
idiopathic generalized epilepsy (2 papers, 2013 to 2016). A generalised epilepsy that encompasses several common seizure phenotypes including childhood absence epilepsy, juvenile absence epilepsy, juvenile myoclonic epilepsy and epilepsy with generalized tonic-clonic seizures alone. "A rare variant in the SLC4A3 gene, Ala867Asp, has been associated with idiopathic generalized epilepsy (IGE) in humans, with carriers exhibiting an increased risk of developing IGE, but SLC4A3 has not been implicated in human retinal disease." (PMID 27211793, 2016).
ovarian carcinoma (2 papers, 2017 to 2023). A malignant neoplasm originating from the surface ovarian epithelium. "Both are intergenic lncRNA, with AC093843.1 (also known as lnc-SLC4A3-9:1) having been associated with poor prognosis in an ovarian cancer study and no function or association ascribed to ENSG00000287527 (also known as lnc-PCDH1-1)." (PMID 37318869, 2023). "By analyzing ovarian cancer datasets with the cBioPortal, we found the highest frequency of AE2 (SLC4A2) gene amplification (TCGA Provisional, 10.0%; TCGA 2011, 4.4%), as compared to AE1 (SLC4A1) (TCGA Provisional, 0.3%; TCGA 2011, 0.3%) and AE3 (SLC4A3) (TCGA Provisional, 2.6%; TCGA 2011, 0.6%)." (PMID 28743911, 2017).
adenoma (1 paper, 2021). A neoplasm arising from the epithelium. "One functional group of transporters to be discussed are Cl−/HCO3− exchangers belonging to the class of SLC (solute carrier) 4 proteins such as AE1 (SLC4A1), AE2 (SLC4A2), and AE3 (SLC4A3), or SLC26 proteins such as DRA (SLC26A3; downregulated in adenoma)." (PMID 33914143, 2021).
congenital stationary night blindness (1 paper, 2007). "Dysfunction in Cav1.4, such as occurs in congenital stationary night blindness (type 2), leads to selective b-wave diminution, with sprouting of bipolar cell dendrites as reported here in Slc4a3−/− retina." (PMID 17786210, 2007).
hemolytic-uremic syndrome (1 paper, 2025). Acute kidney injury associated with microangiopathic hemolytic anemia and thrombocytopenia. "Expression of SLC4A3, which regulates cardiac potential, and CFHR1, associated with an atypical hemolytic-uremic syndrome, were also ruled out." (PMID 40676628, 2025).
lung carcinoma (1 paper, 2021). "SLC4A3 protein acts as an anion exchange protein that has been associated with relapse time in lung cancer." (PMID 33791201, 2021). "The level of CEACAM5 (P < 0.001), CNGB1 (P < 0.001), CSTL1 (P < 0.001), RASAL1 (P < 0.001), SLC4A3 (P < 0.001) expression were also increased in lung tissues of patients with lung cancer coexisting COPD compared to controls." (PMID 33791201, 2021). "In addition, the level of CEACAM5 (P = 0.030), CNGB1 (P = 0.042), CSTL1 (P = 0.046), RASAL1 (P = 0.039), SLC4A3 (P = 0.035) expression were higher in patients with lung cancer coexisting COPD than that in patients with lung cancer alone." (PMID 33791201, 2021).
retinal disease (1 paper, 2016). "Aberrant SLC4A3 has been shown to cause retinal disease in the mouse and dog, making the gene a strong candidate for human retinal disease." (PMID 27211793, 2016). "We report here the first such study to screen human patients with retinal disease for potentially pathogenic mutations in the SLC4A3 gene." (PMID 27211793, 2016). "However, it is difficult to select which variants to test, and the assay to use until more convincing evidence is presented that SLC4A3 is involved in human retinal disease." (PMID 27211793, 2016). "It is therefore possible, if not probable, that mutations in SLC4A3 could cause retinal disease in humans." (PMID 27211793, 2016). "SLC4A3 exons were amplified and sequenced in 200 patients with autosomal recessive retinal degeneration who had no known molecular diagnosis for their condition, which included 197 unrelated individuals with suspected RP and three individuals with other forms of retinal disease." (PMID 27211793, 2016).
tumor (13 papers, 2009 to 2025). "To further explore the functional impact of SLC4A3 somatic mutations, we analysed SLC4A3 expression in tumour samples included in both our transcriptomic and simple nucleotide variation UCEC data." (PMID 37999800, 2024). "Tumours carrying somatic SLC4A3 mutations expressed significantly less SLC4A3 mRNA." (PMID 37999800, 2024).
cancer (8 papers, 2014 to 2025). A tumor composed of atypical neoplastic, often pleomorphic cells that invade other tissues. "In pan-cancer analyses, we find that SLC4A3 ranks as the second most commonly mutated ABT-SLC." (PMID 37999800, 2024). "Among the acid-loading transporter genes, the expressions of SLC4A1AP, SLC4A2, and SLC4A3 are up-regulated or remain unaltered in cancer tissues vs. controls across most of the 14 cancer types." (PMID 31071451, 2019). "Firstly, the mRNA expression levels of most of the SLC4 and SLC26 family members differ widely between normal and cancer tissue, with a clear trend toward upregulation of SLC4A3, SLC4A7, and SLC26A6, and downregulation of SLC4A1 in cancer compared to normal tissue." (PMID 24795638, 2014). "However, widely utilised algorithm-based approaches to detect cancer driver genes do not definitively identify SLC4A3 when considering both p-value and fdr." (PMID 37999800, 2024).
neurological disorders (1 paper, 2025). "Examples include SLC4A3 (AE3), which can act as a Cl− accumulator, and SLC4A10 (NCBE), which mediates sodium-dependent Cl− efflux while allowing bicarbonate influx and has been linked to neurological disorders." (PMID 41010403, 2025).
psychiatric disorder (1 paper, 2024). A disorder characterized by behavioral and/or psychological abnormalities, often accompanied by physical symptoms. "SLC4A3 encodes a bicarbonate transporter; its dysfunction can disturb the brain’s acid-base balance, possibly contributing to neurological and psychiatric disorders, noted for significant variability in individuals who have died by suicide." (PMID 39238930, 2024).
SLC4A3 also shares sentences with these, for which no sentence is quoted: vitreoretinal degeneration (3 papers); breast carcinoma (2); cardiac hypertrophy (2); hypertrophic cardiomyopathy (2); acinar cell carcinoma of the pancreas (1); adenocarcinoma (1); Brugada syndrome (1); cardiac arrhythmia (1); congenital heart disease (1); cyst (1); dysplasia (1); embryonal carcinoma (1); gastrointestinal tumors (1); hypertrophy (1); invasive lobular carcinoma (1); lymphoma (1); mesothelioma (1); metanephric adenoma (1); myoepithelial neoplasm (1); nasopharyngeal carcinoma (1); Nephroblastoma (1); oral squamous cell carcinoma (1); Retinal atrophy (1); retinitis pigmentosa (1); sarcoma (1); schizophrenia (1); sebaceous carcinoma (1); squamous cell carcinoma (1); thyroiditis (1); ventricular fibrillation (1).